IGF1R (insulin like growth factor 1 receptor)
Diseases named in the same sentence as IGF1R in open-access papers (continued):
Sharing a sentence is not in itself a finding about the gene and the disease.
acute lymphoblastic leukemia (18 papers, 2010 to 2025). Leukemia with an acute onset, characterized by the presence of lymphoblasts in the bone marrow and the peripheral blood. "We previously found that T-cell acute lymphoblastic leukemia (T-ALL) requires support from tumor-associated myeloid cells, which activate Insulin Like Growth Factor 1 Receptor (IGF1R) signaling in leukemic blasts." (PMID 37805579, 2023). "IGF1R expression was shown to be significantly higher in CML than in acute lymphoblastic leukemia (ALL)." (PMID 29455671, 2018). "In T-cell acute lymphoblastic leukemia (T-ALL), the Notch-regulated cheRNA LUNAR1 binds to the enhancer of IGF1R, activates the promoter of IGF1R in cis, maintains a high level of mRNA expression, and promotes the growth of T-ALL." (PMID 33937246, 2021). "In human T cell acute lymphoblastic leukemia (T-ALL), the lncRNA LUNAR1 is regulated by the Notch pathway and is necessary for efficient T-ALL growth through enhancement of IGF1R mRNA expression." (PMID 29403493, 2018). "•Dual insulin-like growth factor 1 receptor (IGF1/R) + mitogen-activated protein kinase/extracellular signal-regulated kinase (ERK) kinase (MEK) inhibition synergistically sensitize apoptosis-resistant acute lymphoblastic leukemia (ALL) cells." (PMID 29656114, 2018). "miR- 101 has been described to be a pro-apoptotic factor in childhood acute lymphoblastic leukemia and miR-7 as an tumor suppressor inhibiting various receptor tyrosine kinases such as EGFR, IGF-1R and p21 activated kinase (PAK1)." (PMID 27542283, 2016).
atherosclerosis (18 papers, 2016 to 2025). A disease characterized by the build-up of fatty material and calcium deposition in the arterial wall resulting in partial or complete occlusion of the arterial lumen. "In this study, EGFR, VEGFA, HSP90AA1, SRC, HIF1A, CXCR4 and IGF1R were identified as key hub targets, which linked anthocyanins with atherosclerosis." (PMID 40478326, 2025). "Furthermore, endothelial deficiency of IGF-1 receptor (IGF1R) caused endothelial barrier dysfunction and promoted atherosclerosis in ApoE-deficient mice." (PMID 40478326, 2025). "We demonstrate for the first time that increasing endothelial IGF-1R reduces atherosclerosis, modifies vascular endothelial junctions, reduces leakage between endothelial cells, and suppresses endothelial LDL-cholesterol uptake." (PMID 40171617, 2025). "Recent studies indicate that IGF-1 exerted both pleiotropic antioxidant effects and anti-inflammatory effects, which reduced atherosclerotic burden, while losing IGF1R on smooth muscle promoted atherosclerosis." (PMID 35882857, 2022). "To take this a step further, we expressed mutant IGF-1R in SVECs from patients with advanced atherosclerosis and demonstrated a reduction in mIR-25 expression and an increase in Nox4 expression." (PMID 34420367, 2021). "In accordance with this study our results indicated that miR-223 and IGF-1R directly improve late EPC functional properties in atherosclerosis by stimulating the proliferation and migration abilities." (PMID 31068820, 2019). "Moreover, we provide evidences that the presence of healthy origin platelets is of utmost importance on functional improvement of EPCs in atherosclerosis by miR-223 transfer and subsequent targeting of the chemokines and IGF-1R." (PMID 31068820, 2019). "Therefore, our data suggest that the positive effects of healthy platelets on late EPC function in atherosclerosis can be explained by increasing miR-223 levels that target IGF-1R as results of their transfer from platelets." (PMID 31068820, 2019). "The identification of the selective actions of homo-IR that can be inhibited by IGF1R is exciting especially with the identification of a IR-specific downstream target, Has2, which has already shown to be important for restenosis and possible atherosclerosis." (PMID 31562314, 2019). "Furthermore, testing the direct effect of miR-223 and IGF-1R on late EPCs disclosed that these molecular factors improve late EPC functional properties in atherosclerosis in terms of stimulation of the proliferation and migration abilities." (PMID 31068820, 2019). "Therefore, identification of the miR-138 and miR-133a-IGF-1R pathways might provide insight into the design of an efficient therapeutic approach to suppress atherosclerosis." (PMID 28097140, 2016). "The PI3K-Akt signaling pathway is involved in atherosclerosis by blocking blood flow and inhibiting the migration of fibroblasts and can suppress neuronal cell death and improve tau hyperphosphorylation by BCL2, GSK3B, and IGF1R." (PMID 32802132, 2020). "miR-138 promotes the proliferation and migration of VSMCs in db/db mice by suppressing the expression of SIRT1, and miR-133a serves as a stimulatory factor for IGF-1R expression by prolonging the half-life of IGF-1R mRNA and promoting IGF-1-induced VSMC proliferation in murine atherosclerosis." (PMID 28097140, 2016).
medulloblastoma (17 papers, 2009 to 2024). A malignant, invasive embryonal neoplasm arising from the cerebellum. "Together, our studies identify IGF1R as a high value target for clinical trials in high risk medulloblastoma." (PMID 27255663, 2016). "Of relevance, IGF-1R was also identified as a therapeutic target in medulloblastoma, a highly aggressive pediatric malignancy of the cerebellum." (PMID 37259440, 2023). "For these genes, probes were significantly differentially expressed across samples as determined by Student’s t-test in medulloblastoma samples for IGF1R (5/ 5), SERPINE1 (7/7)." (PMID 27255663, 2016). "In parallel, studies of key factors responsible for cell autonomous growth in MYC amplified medulloblastoma prioritized IGF1R inhibitors." (PMID 27255663, 2016). "IGF-1R is highly expressed in a majority of medulloblastoma, with one series reporting that 80% of medulloblastomas highly express IGF-1R." (PMID 23383402, 2013). "The profile of R1507 in neuro- and medulloblastoma was similar to the IGF-1R tyrosine kinase inhibitor NVP-AEW541 in terms of the identity of the cell lines which were sensitive to the single agent." (PMID 23056595, 2012). "Recently, genes associated with receptor tyrosine kinase-phosphoinositide 3-kinase signaling were found to be selectively altered in SHH medulloblastoma, including amplifications of IGF1R, insulin receptor substrate 2 as well as focal deletions of PTEN on chromosome 10q23.3112." (PMID 27255663, 2016). "In addition, IGF1/IGF1R signaling in the TME was found to be critical for medulloblastoma growth." (PMID 35688943, 2022). "Cell viability screening of targeted small molecule inhibitors further prioritized IGF1R inhibitors for the metastatic, MYC amplified medulloblastoma tumor cell cultures." (PMID 27255663, 2016). "ERK1/2 activation in medulloblastomas can occur following activation of growth factor receptors, such as EGFR, PDGFR, IGF1R and CXCR4." (PMID 19594892, 2009). "When hAT-MSCs were co-cultured with medulloblastoma-BTICs, the expression levels of CCR4, CCR5, CCR7, XCR1, CXCR1, CXCR4, PDGFR-bb, KDR and TEK were increased, while the levels of CX3CR1, IL1R, IL6R, IL8R, IGF1R and CD44 were decreased (p<0.05)." (PMID 26076490, 2015).
gastrointestinal stromal tumor (16 papers, 2010 to 2022). "Interesting data have been reported also on IGF1r in gastrointestinal stromal tumors (GISTs) especially in children and in young adult patients whose disease does not harbour mutations on KIT and PDGFRA and are poorly responsive to conventional therapies." (PMID 21078151, 2010). "Interestingly, there are now also single cases of breast and lung cancers, ALK-negative inflammatory myofibroblastic tumors (IMTs), and gastrointestinal stromal tumors (GISTs) described with chimeric fusions in which IGF1R serves as the 3’-partner gene." (PMID 31426421, 2019). "Interesting data have been reported on IGF1R in gastrointestinal stromal tumors (GISTs)." (PMID 21078151, 2010). "Gastrointestinal stromal tumors (GISTs) lacking of KIT and PDGFRα mutations presented significantly higher prevalence of IGF-1R amplification compared to mutated ones." (PMID 22415797, 2012).
Graves disease (16 papers, 2012 to 2025). Graves' disease is an autoimmune disorder that leads to overactivity of the thyroid gland (hyperthyroidism).It is caused by an abnormal immune system response that causes the thyroid gland to produce too much thyroid hormones. "This study aims to develop a peptide probe, 99mTc-ZIGF1R:4551-GGGC, targeting the IGF-1R, and to achieve specific imaging in Graves’ disease (GD) animal models exhibiting GO." (PMID 39920417, 2025). "In this study, we evaluate the effect of linsitinib, also known as OSI-906, a novel, highly selective small-molecule dual inhibitor of the IGF-1R and IR on the outcome of Graves’ disease." (PMID 37435490, 2023). "Activation of insulin-like growth factor-1 receptor (IGF-1R) signaling and overexpression of IGF-1R in the orbital fibroblasts, B cells and T cells were reported in Graves’ disease patients." (PMID 35837312, 2022). "Graves’ disease (GD) is the most common cause of hyperthyroidism mediated by autoantibodies against the TSH receptor (TSHR) and the insulin-like growth factor 1 receptor (IGF-1R)." (PMID 39685806, 2024). "IGF-1R is over-expressed by orbital fibroblasts in the autoimmune syndrome, Graves' disease (GD)." (PMID 22506015, 2012). "Importantly, anti-IGF-1R antibodies have turned out to be useful in Graves' disease." (PMID 39638246, 2024). "Here, we investigated in an experimental murine model of Graves’ disease, whether autoimmune GD and TED associates with bone marrow activation and whether linsitinib, an oral small molecule inhibitor of the IGF-1R and insulin receptor (IR), interferes with this activation process." (PMID 37810891, 2023). "The Graves’ disease (GD) specific autoantigen thyrotropin receptor (TSH-R) and the insulin-like growth factor 1 receptor (IGF-1R) are molecular targets on both thyrocytes and orbital fibroblasts playing pivotal roles in the pathogenesis of GD and thyroid eye disease (TED)." (PMID 39723207, 2024). "In the present study, we investigated the role of bone marrow cells during development of experimental Graves’ disease and TED and whether the bone marrow is involved in the immune inhibitory effect of the IGF-1R/IR antagonist linsitinib." (PMID 37810891, 2023). "Here, we investigated whether induction of experimental Graves’ disease and accompanying TED involves bone marrow activation and whether interference with IGF-1R signaling prevents this activation." (PMID 37810891, 2023). "We confirmed that diosgenin can bind to IGF-1R and inhibit the activation of Akt and ERK pathways by inhibiting the phosphorylation of IGF-1R, resulting in increasing apoptosis of hyperproliferated thyroid cells in Graves’ disease and alleviating goiter." (PMID 35140607, 2021). "By blocking the IGF-1R mediated signaling through the AKT-mTOR pathway, linsitinib might have a reverse effect on the Th17/Treg balance, by suppressing the proinflammatory cytokine Th17 and enhancing Treg development and therefore has a positive effect on the outcome of Graves’ disease." (PMID 37435490, 2023).
head and neck cancer (16 papers, 2011 to 2025). A primary or metastatic malignant neoplasm affecting the head and neck. "Increased IGF‐1R signalling is associated with a poor response to anti‐EGFR treatment in head and neck cancer cells." (PMID 34528373, 2021). "In head and neck cancer, let-7 insulin-like growth factor 1 receptor (IGF1R) pathway is possibly linked with cancer cell migration and invasion." (PMID 22645613, 2012). "In addition to the EGFR RTK family, other RTKs like IGF-1R are frequently activated in up to 94% of patient samples and have been implicated in driving head and neck cancer progression." (PMID 40560045, 2025). "A newly developed biomarker reveals upregulation of an antiapoptotic IGF1R-integrin-syndecan receptor complex in head and neck cancer and documents disruption of the complex in patient-derived tumor xenografts (PDX) treated with the inhibitor SSTNIGF1R." (PMID 36968227, 2023). "In this study, we analyzed the immediate early molecular response of cetuximab on physical interactions between EGFR and Insulin growth factor 1 like receptor (IGF-1R) in head and neck cancer cells that are resistant to cetuximab." (PMID 27716204, 2016). "Interest in targeting the IGF-1R in HNSCC was bolstered by the observation that treatment of head and neck cancer cells with either IGF or EGF resulted in IGF-IR and EGFR heterodimerization." (PMID 21776391, 2011). "Targeted therapies that block EGFR, Met, and IGF-1R signaling in head and neck cancers continue to show promising results in preclinical studies and clinical trials." (PMID 21776391, 2011). "Another promising RTK under preclinical and clinical evaluation for head and neck cancers includes the IGF-1R." (PMID 21776391, 2011). "IGF-1R was reported to be capable of transmitting mitogenic signals to the neoplastic cells and may be a possible target of immunotherapy in the head and neck carcinomas." (PMID 32922441, 2020). "Targeting of EGFR and IGF-1R in a spatio-temporal manner could be a promising therapeutic strategy in head and neck cancer." (PMID 27716204, 2016). "The recently reported head and neck cancer TCGA has identified 4 % amplification and mutation of IGF1R gene in HPV negative HNSCC patients." (PMID 27716204, 2016). "Our results suggest that a combinatorial approach that inhibits both EGFR and IGF1R signaling may offer a worthy strategy to enhance therapeutic outcome and combat acquired resistance to cetuximab in head and neck cancer." (PMID 27716204, 2016). "However, the mechanism by which IGF-1R crosstalks with EGFR and its impact on head and neck cancer disease progression remains elusive." (PMID 40560045, 2025). "The apparent cooperation between IGF-1R and EGFR in promoting HNSCC pathogenesis as well as resistance to EGFR-targeted therapy, suggests an advantage to cotargeting these signaling axes for the treatment of head and neck cancers." (PMID 21776391, 2011).
heart failure (16 papers, 2010 to 2025). Inability of the heart to pump blood at an adequate rate to meet tissue metabolic requirements. "IGF1Rtg causes increased IGF1R signalling, leading to elevated mTOR activity and autophagy inhibition, as well as age-associated heart failure, which can be overridden by SPD42." (PMID 39117797, 2024). "Knock-out of IGF-1R in cardiac muscle increased early-onset dilated cardiomyopathy and heart failure in mice." (PMID 37569355, 2023). "Together, these data indicate that combined loss of IR/IGF1R or IRS1/IRS2 signaling in the adult heart results in impaired insulin-mediated signaling, heart failure, and increased mortality." (PMID 36125265, 2022). "Earlier studies have described heart failure in mouse models following embryonic or perinatal deletion of essential proteins involved in the IR/IGF1R signaling pathway, i.e., IR/IGF1R, IRS1/2 (13, –, 15), and mTOR." (PMID 36125265, 2022). "It should be noted that phosphorylation of IGF1R is suppressed in atrial fibrillation and heart failure." (PMID 32408527, 2020). "Mice carrying a deletion of both IR and IGF-1R in the skeletal muscle and heart display a severe impairment of cardiac function and die of heart failure four weeks after birth." (PMID 21084725, 2010). "Atrial enlargement in the DCM-dnPI3K Tg, but not IGF1R Tg, was associated with atrial dysfunction, fibrosis and a heart failure gene expression pattern." (PMID 39018488, 2024). "We therefore tested the hypothesis that loss of IR/IGF1R and IRS1/2 signaling in adult hearts would impair mitochondrial oxidative capacity to precipitate heart failure in iCIR2KO and iCIRS12KO hearts." (PMID 36125265, 2022). "Thus, distinct mechanisms contribute to heart failure following disruption of IR/IGF1R signaling in the embryonic relative to the adult heart." (PMID 36125265, 2022). "Loss of signaling through these interaction partners could potentially result in heart failure in IRS1/2-deficient hearts by mechanisms that are independent of IR/IGF1R signaling." (PMID 36125265, 2022). "Thus, the mechanism by which loss of IR/IGF1R signaling perturbs the expression of cardiac structural proteins to induce heart failure is not a generalized mechanism that is applicable to models of heart failure induced by hemodynamic stress." (PMID 36125265, 2022). "Furthermore, we found that the absence of IGF1R caused a decrease left ventricular remodelling in conditions of sustained biomechanical stress, such as eccentric hypertrophy, thus accelerating the transition towards heart failure." (PMID 24965872, 2014). "Perturbed sarcomeric structure observed in iCIR2KO and iCIRS12KO hearts is likely a consequence of impaired IR/IGF1R/Akt signaling and not a consequence of heart failure per se." (PMID 36125265, 2022). "Thus, distinct mechanisms mediated by IR/IGF1R and IRS1/2 contribute to heart failure following embryonic deletion versus inducible deletion of these signaling proteins in the adult heart." (PMID 36125265, 2022). "Both ErbB2 and IGF1R share downstream proteins that are pro-survival in nature, explaining why heart failure is not seen with over-expression of these proteins." (PMID 22912742, 2012). "The propensity to cause hypertrophy without heart failure is also seen with over-expression of insulin-like growth factor 1 (IGF-1) and insulin-like growth factor 1 receptor (IGF1R)." (PMID 22912742, 2012). "Here, we identify a role for IR/IGF1R-mediated signaling in regulating a serum response factor (SRF)-mediated transcriptional program necessary for sarcomeric integrity in the adult heart, which if absent results in rapid development of heart failure." (PMID 36125265, 2022).